AGAP2 (ArfGAP with GTPase domain, ankyrin repeat and PH domain 2)
Description:
GTPase-activating protein (GAP) for ARF1 and ARF5, which also shows strong GTPase activity. Isoform 1 participates in the prevention of neuronal apoptosis by enhancing PI3 kinase activity. It aids the coupling of metabotropic glutamate receptor 1 (GRM1) to cytoplasmic PI3 kinase by interacting with Homer scaffolding proteins, and also seems to mediate anti-apoptotic effects of NGF by activating nuclear PI3 kinase. Isoform 2 does not stimulate PI3 kinase but may protect cells from apoptosis by stimulating Akt. It also regulates the adapter protein 1 (AP-1)-dependent trafficking of proteins in the endosomal system. It seems to be oncogenic. It is overexpressed in cancer cells, prevents apoptosis and promotes cancer cell invasion.
Synonyms: GGAP2; PIKE; CENTG1
Tractability: Small molecule: it has a binding pocket of medium quality. PROTAC: ubiquitination databases record sites on it; its protein half-life has been measured.
Gene: Protein-coding gene on chromosome 12 (57,723,761 to 57,742,157, reverse strand). Ensembl gene ENSG00000135439.
Subcellular location: Cytoplasm (Isoform 1); Nucleus; Cytoplasm (Isoform 2)
Subcellular location (Human Protein Atlas): Cytosol; Nucleoplasm; Midbody ring
Pathways (Reactome):
Developmental Biology: Netrin-1 signaling
Gene Ontology:
Molecular function: ATP binding; GTP binding; GTPase activator activity; GTPase activity; phosphatidylinositol 3-kinase regulator activity; protein binding; protein kinase activator activity; protein kinase binding; phosphatidylinositol 3-kinase activator activity
Biological process: actin cytoskeleton organization; endosomal transport; negative regulation of neuron apoptotic process; negative regulation of protein catabolic process; positive regulation of protein kinase activity; negative regulation of apoptotic process
Cellular component: cytoplasm; cytosol; endosome; extracellular exosome; membrane; nucleoplasm; nucleus
Genetic constraint (gnomAD): Loss-of-function variants: 33 observed, 106.57 expected, observed/expected ratio (o/e) 0.31, 90% interval 0.23 to 0.41. The upper end of that interval is the gene's LOEUF score, 0.41, which puts it in group 1 of 6, group 1 being the genes least tolerant of losing a copy. Missense variants: 1,285 observed, 1,491.9 expected, observed/expected ratio (o/e) 0.86, 90% interval 0.82 to 0.9. Synonymous variants: 702 observed, 654.51 expected, observed/expected ratio (o/e) 1.07, 90% interval 1.01 to 1.14.
Homologues: Orthologues: chimpanzee AGAP2 (99% identical), macaque AGAP2 (98% identical), pig AGAP2 (97% identical), guinea pig AGAP2 (96% identical), dog AGAP2 (95% identical), mouse Agap2 (95% identical), rat Agap2 (91% identical), rabbit AGAP2 (66% identical), tropical clawed frog agap2 (54% identical), zebrafish agap2 (37% identical). Paralogues in human: AGAP1 (37% identical), AGAP3 (36% identical), AGAP5 (25% identical), AGAP6 (25% identical), AGAP4 (24% identical), AGAP9 (22% identical), ASAP1 (13% identical), ASAP3 (13% identical), ASAP2 (12% identical), ACAP3 (12% identical), ACAP2 (12% identical), ACAP1 (11% identical), and 16 more.